EIF4EBP1 (eukaryotic translation initiation factor 4E binding protein 1)
Diseases named in the same sentence as EIF4EBP1 in open-access papers (continued):
Sharing a sentence is not in itself a finding about the gene and the disease.
ovarian carcinoma (26 papers, 2010 to 2024). A malignant neoplasm originating from the surface ovarian epithelium. "Increased expression of miR-125b inhibited the invasion and migration of ovarian cancer cells and was associated with decreased expression of EIF4EBP1 (eukaryotic translation initiation factor 4E-binding protein 1)." (PMID 37443682, 2023). "Increased expression of miR-125a and miR-125b inhibited invasion and migration of SKOV3 and OVCAR-429 ovarian cancer cells and was associated with a decrease in EIF4EBP1 expression." (PMID 26646586, 2016). "The downregulation of miR-125a and miR-125b was also observed in ovarian cancer patients, accompanied by a significant increase in EIF4EBP1 mRNA expression." (PMID 26646586, 2016). "The aim of the present study was to identify the specific miRNAs involved in EIF4EBP1 expression in ovarian cancer cells and to define their functional effects." (PMID 26646586, 2016). "miR-125a and miR-125b overexpression significantly decreased proliferation of ovarian cancer cells within 48 to 72 h of treatment, as did the knockdown of EIF4EBP1." (PMID 26646586, 2016). "In keeping with our in vitro findings, we found that EIF4EBP1 expression was significantly elevated in ovarian cancer tissue and cell lines and that protein levels were strongly associated with prognosis of patients with ovarian cancer." (PMID 26646586, 2016). "The aim of the present study was to identify the specific miRNAs involved in regulation of EIF4EBP1 expression in ovarian cancer and to define their biological function." (PMID 26646586, 2016). "In keeping with our in vitro and in vivo results, we found that EIF4EBP1 mRNA expression was significantly higher in ovarian cancer tissue than in normal ovarian surface epithelium (P < 0.001)." (PMID 26646586, 2016). "In this study, we elucidated the post-transcriptional inhibition of EIF4EBP1-mediated pathways in ovarian cancer cells by the miRNAs miR-125a and miR-125b." (PMID 26646586, 2016). "Taken together, these results demonstrate that miR-125a- and miR-125b-mediated suppression of EIF4EBP1 plays an important role in cell invasion and mobility in ovarian cancer." (PMID 26646586, 2016). "Furthermore, miR-125b inhibited invasion and migration of ovarian cancer cells through posttranscriptional down-regulation of EIF4EBP1 expression." (PMID 28881624, 2017). "EIF4EBP1 was significantly elevated in ovarian cancer cells relative to control cells." (PMID 26646586, 2016). "In case studies, EIF4EBP1 alteration was strongly related to survival in ovarian cancer patients." (PMID 26646586, 2016). "However, it is unclear how EIF4EBP1 transcripts are regulated in ovarian cancer." (PMID 26646586, 2016). "Thus, we postulated that aberrantly-expressed miRNAs—whether over-expressed tumorigenic miRNAs or under-expressed protective miRNAs—contribute to the development of ovarian cancer by upregulating EIF4EBP1 expression." (PMID 26646586, 2016). "Moreover, EIF4EBP1, the target gene of has_circ_0007905/miR-6749-3p, has been reported to be extensively involved in cell proliferation and apoptosis, such as in acute myeloid leukemia cells, ovarian cancer cells (Lee, Kim & Jeon, 2016), and extravillous trophoblast cells." (PMID 36908822, 2023). "First, using specific miR mimics, we investigated whether overexpression of miR-125a or miR-125b was sufficient to reduce EIF4EBP1 levels in SKOV3 and OVCAR-429 ovarian cancer cells." (PMID 26646586, 2016).
melanoma (25 papers, 2005 to 2025). A malignant, usually aggressive tumor composed of atypical, neoplastic melanocytes. "These genes contained KDELR3, EIF4EBP1, TARS, MTHFD2, SHC1 which all highly expressed in melanoma compared to normal skin in The Human Protein Atlas." (PMID 33136551, 2020). "In this research, we further distinguished 5 differentially expressed UPRRGs (KDELR3, EIF4EBP1, TARS, MTHFD2 and SHC1), which also highly expressed in melanoma at the protein level." (PMID 33136551, 2020).
colorectal cancer (22 papers, 2014 to 2025). A primary or metastatic malignant neoplasm that affects the colon or rectum. "In colorectal cancer, downstream molecules of the mTOR pathway such as eukaryotic translation initiation factor 4E (eIF4E) and eukaryotic translation initiation factor 4E-binding protein 1 (4E-BP1), play a crucial role in cancer development." (PMID 39349424, 2024). "CIRC-Erbin sponges miR-125a-5p and miR-138-5p, targeting eukaryotic translation initiation factor 4E-binding protein 1 (4EBP-1) and accelerating HIF-1α capsid protein translation in colorectal cancer cells." (PMID 37394582, 2023).
hepatocellular carcinoma (20 papers, 2012 to 2025). A malignant tumor that arises from hepatocytes. "High expression of EIF4EBP1 is associated with poorer survival and worse disease progression in patients with hepatocellular carcinoma." (PMID 37866481, 2023). "EIF4EBP1 contributes to carcinogenesis in lung adenocarcinoma, hepatocellular carcinoma, and nasopharyngeal carcinoma, and its suppression inhibits ccRCC cell proliferation, migration, and invasion." (PMID 40591061, 2025). "High expression of EIF4EBP1 in hepatocellular carcinoma tissues correlates with poor patient prognosis." (PMID 31626592, 2019). "For example, EIF4EBP1 is reported to be significantly overexpressed in hepatocellular carcinoma (HCC) tissues and is related to poor survival of patients with HCC." (PMID 34743716, 2021). "For example, EIF4EBP1 is reported to be significantly overexpressed in hepatocellular carcinoma (HCC) tissues and is related to poor survival of HCC patients." (PMID 34743716, 2021). "Previous studies showed that EIF4EBP1 acts as an oncogene in lung adenocarcinoma, hepatocellular carcinoma, and nasopharyngeal carcinoma, but no one has studied the biological effect of EIF4EBP1 in ccRCC." (PMID 34922539, 2021). "However, the clinical significance and biological role of EIF4EBP1 in hepatocellular carcinoma (HCC) have not been elucidated." (PMID 25658620, 2015).
Obesity (19 papers, 2014 to 2025). Accumulation of substantial excess body fat. "Long-term high-fat, high-sugar diets, obesity, and nutrient excess activated mTOR, which activated its downstream effector proteins, P70 ribosomal protein S6 kinase 1 (p70S6K1) and eukaryotic translation initiation factor 4E-binding protein 1 (4E-BP1)." (PMID 37898776, 2023).
acute myeloid leukemia (18 papers, 2010 to 2025). Acute myeloid leukemia (AML) is a group of neoplasms arising from precursor cells committed to the myeloid cell-line differentiation. "Here, we set out to investigate the potential of the BP-regulated ALKBH5/MLST8/EIF4EBP1 axis on prevention and treatment of acute myeloid leukemia (AML)." (PMID 35579750, 2022). "Our data indicate that BP can inhibit acute myeloid leukemia cell proliferation by downregulating ALKBH5-mediated m6A demethylation of EIF4EBP1 and MLST8 mRNAs, which may have potential to prevent and treat this disease." (PMID 35579750, 2022).
pancreatic cancer (18 papers, 2013 to 2023). "In fact, treatment with the SOCE inhibitor RP4010 in pancreatic cancer led to reduced NFAT translocation and increased expression of eukaryotic translation initiation factor 4E-binding protein 1 (EIF4EBP1)." (PMID 33919156, 2021).
cervical carcinoma (17 papers, 2014 to 2024). A carcinoma arising from either the exocervical squamous epithelium or the endocervical glandular epithelium. "Overexpression of phosphorylated EIF4EBP1 is closely associated with tumor recurrence and worse survival outcomes of cervical cancer." (PMID 31967976, 2020). "The expression of seven hub genes in the PI3K/AKT/mTOR pathway were increased in cervical cancer: EIF4EBP1, GSK3B, HRAS, KRAS, NRAS, PIK3CB and PIK3R2." (PMID 36911370, 2023). "In BC and cervical cancer, EIF4EBP1 is considered to be a major factor in the signaling pathway related to prognosis and malignancy, which was not changed by the presence of other upstream carcinogens, it is consistent with our findings." (PMID 36524001, 2022). "Noticeably, eukaryotic translation initiation factor 4E binding protein 1 (4EBP1) and EPH receptor A2 (EPHA2), which play important role in progression of cervical cancer, particularly in regulating migration and invasion, were hyperphosphorylated." (PMID 39567474, 2024). "Induction of ER-stress in cervical carcinoma cells (HeLa) by glucose deprivation showed early upregulation of ATF4 and other target genes of this stress response pathway such as DDIT3, GADD34, ATF3, and EIF4EBP1 at 24 h." (PMID 33413684, 2021).
diabetes (16 papers, 2012 to 2025). "Our results are similar to those of previous reports showing that the deficiency of the genes induced by ATF4, such as Eif4ebp1 and Atf5, exacerbated hyperglycemia in the mouse models of diabetes." (PMID 34547510, 2021).
bladder cancer (13 papers, 2011 to 2024). "We found that phosphorylation of EIF4EBP1 was significantly reduced in the TalaA-treated group, indicating that TalaA inhibits translation in bladder cancer cells by downregulating EIF4EBP1 phosphorylation." (PMID 37866481, 2023).
neuroblastoma (12 papers, 2013 to 2025). Neuroblastoma (NB) is the most common solid, extracranial childhood tumor. "In line with that, we observed that EIF4EBP1 mRNA expression in Group 4 MBs is associated with elevated MYCN mRNA expression, as we previously reported in neuroblastoma." (PMID 40670359, 2025). "Similarly, Hcy treatment caused significant increases in the level of MTOR phosphorylation and its downstream substrates RPS6KB1/p70S6K and EIF4EBP1 in human neuroblastoma SH-SY5Y cells." (PMID 27929536, 2016).
cardiac hypertrophy (10 papers, 2019 to 2025). "Akt can inhibit the eukaryotic translation initiation factor 4E-binding protein 1(4E-BP1) and upregulate the CBP/p300- interacting transactivator with ED-richcarboxy-terminal domain 4 (CITED4) to enhance cardiac hypertrophy." (PMID 36834623, 2023).
mesothelioma (10 papers, 2009 to 2023). A usually malignant and aggressive neoplasm of the mesothelium which is often associated with exposure to asbestos. "For example, the PI3K/AKT signaling pathway regulating the cell cycle is aberrantly active in MPM, and the mesothelioma gene FGFR1 is connected to this pathway via its novel predicted PPIs with EIF4EBP1 and PRP2CB." (PMID 33916178, 2021).
sarcopenia (10 papers, 2017 to 2025). Progressive decline in muscle mass due to aging which results in decreased functional capacity of muscles. "Dr. Shih-Yin Tsai (National University of Singapore, Singapore) showed that eukaryotic translation initiation factor 4E (eIF4E) binding protein 1 (EIF4EBP1 or 4E-BP1) activation proved to be beneficial in sarcopenia, where the proteostasis is disrupted." (PMID 41245273, 2025).
lung adenocarcinoma (9 papers, 2018 to 2026). A carcinoma that arises from the lung and is characterized by the presence of malignant glandular epithelial cells. "In lung adenocarcinoma, the main molecular pathway implicated in the drug action was a downregulation of eukaryotic translation initiation factor 4E-binding protein 1 (EIF4EBP1), known to play critical roles in the tumorigenesis and progression of solid tumors." (PMID 40333626, 2025). "Clinical analysis revealed subtype-specific prognostic value, where high EIF4EBP1 expression correlated with poor survival in lung adenocarcinoma (LUAD) but favorable outcomes in squamous cell carcinoma (LUSC)." (PMID 41769099, 2026).
Cachexia (7 papers, 2011 to 2022). Severe weight loss, wasting of muscle, loss of appetite, and general debility related to a chronic disease. "The total levels of S6 and eukaryotic translation initiation factor 4E binding protein 1 (4E‐BP1) are significantly altered in the C26 cachexia model." (PMID 34741441, 2022).
head and neck squamous cell carcinoma (7 papers, 2019 to 2025). A squamous cell carcinoma that arises from any of the following anatomic sites: lip and oral cavity, nasal cavity, paranasal sinuses, pharynx, larynx, and salivary glands. "Loss of EIF4EBP1 is associated with poor overall survival in patients with head and neck squamous cell carcinomas (HNSCC)." (PMID 35480110, 2022).
osteosarcoma (6 papers, 2010 to 2026). A usually aggressive malignant bone-forming mesenchymal neoplasm, predominantly affecting adolescents and young adults. "Taken together, these data suggest that the proliferative effect of PAFAH1B3 in osteosarcoma is related to the regulation of the expression of EIF4EBP1, MYC, PTGS2 and RPS6KB1." (PMID 34136395, 2021). "In consistence with the literature, we found EIF4EBP1, MYC, PTGS2 were down-regulated in PAFAH1B3 knockdown osteosarcoma cells, resulting the deficiency in tumor growth and proliferation." (PMID 34136395, 2021). "Furthermore, the proliferative effect of PAFAH1B3 in osteosarcoma was related to the regulation of the expression of EIF4EBP1, MYC, PTGS2 and RPS6KB1." (PMID 34136395, 2021).
renal carcinoma (6 papers, 2014 to 2025). A carcinoma arising from the epithelium of the renal parenchyma or the renal pelvis. "To assess the importance of these 11 MMCGs, we employed Gene Dependency Scores (gDS) and found that BIRC5, PLG, and EIF4EBP1 had gDS scores below zero in most renal cancer cell lines." (PMID 40591061, 2025). "The results showed that EIF4EBP1, FOXM1, PLG, and VWF were highly expressed in renal carcinoma compared with normal renal tissue, and ADAM8, CGN, G6PC, ITIH4, and MMP3 were low in expression in renal carcinoma compared with normal renal tissue." (PMID 33968297, 2021).
clear cell renal cell carcinoma (5 papers, 2021 to 2025). "The hsa_circ_0020303 induces clear cell renal cell carcinoma (ccRCC) progression by sponging miR-125a-5p, which promotes eukaryotic translation initiation factor 4E binding protein 1 (EIF4EBP1) expression." (PMID 40710359, 2025). "The proliferative and metastatic capacities of cells in clear cell renal cell carcinoma are facilitated by CHST15 through the signaling pathway involving miR-125a-5p/EIF4EBP1, indicating its potential as a promising prognostic biomarker." (PMID 37812215, 2023).
COVID-19 (5 papers, 2021 to 2024). A disease caused by infection with severe acute respiratory syndrome coronavirus 2. "Among them, serum levels of IL-10RB, FGF-19, and CCL-2 positively contributed to both hospitalized and critical COVID-19 conditions (OR: 1.10~1.16), while the other 4 proteins conferred risk on critical COVID-19 only (OR: 1.07~1.16), including EIF4EBP1, IL-7, NTF3, and LIF." (PMID 38455043, 2024). "Less is known about connections between phenotypes of COVID-19 and the levels of FGF-19, EIF4EBP1, and Neurotrophin-3 (NTF3)." (PMID 38455043, 2024).
heart failure (4 papers, 2020 to 2024). Inability of the heart to pump blood at an adequate rate to meet tissue metabolic requirements. "After intersecting the results of the three algorithms, we obtained four down-regulated key aging genes in heart failure, namely BCL6, EIF4EBP1, MEIS2, and SMARCA2." (PMID 38686376, 2024).
dilated cardiomyopathy (3 papers, 2015 to 2022). Cardiomyopathy which is characterized by dilation and contractile dysfunction of the left and right ventricles. "In contrast, genomic deletion of mTOR in the adult mouse myocardium resulted in a fatal, dilated cardiomyopathy characterized by apoptosis, autophagy, altered mitochondrial structure, and accumulation of eukaryotic translation initiation factor 4E-binding protein 1 (4E-BP1)." (PMID 25880554, 2015).
liver cancer (3 papers, 2022 to 2025). An epithelial or non-epithelial malignant neoplasm that arises from the liver. "In breast and liver cancer, high EIF4EBP1 expression has been associated with poor survival." (PMID 35379801, 2022). "Beyond NB, EIF4EBP1 expression was reported to be a factor of poor prognosis in breast and liver cancers, as well as in all TCGA tumor types combined." (PMID 35379801, 2022).
squamous cell carcinoma (3 papers, 2019 to 2026). A carcinoma arising from squamous epithelial cells. "For instance, a hyperactivated mutation in eukaryotic translation initiation factor 4E binding protein 1 (4E-BP1), a downstream effector of mTOR that forms its transcription complex, is commonly observed in the head and neck squamous cell carcinomas." (PMID 35244142, 2022). "MR analysis indicated a potential causal effect of genetically predicted EIF4EBP1 expression on increased LUAD risk (OR = 4.196, 95% CI: 1.209-14.565), but not squamous cell carcinoma." (PMID 41769099, 2026).
Stroke (3 papers, 2020 to 2023). Sudden impairment of blood flow to a part of the brain due to occlusion or rupture of an artery to the brain. "Furthermore, stroke induced the upregulation of genes involved in PI3K-Akt suppression, such as eIF4EBP1 and Mknk2." (PMID 32629989, 2020).
atherosclerosis (2 papers, 2022 to 2025). A disease characterized by the build-up of fatty material and calcium deposition in the arterial wall resulting in partial or complete occlusion of the arterial lumen. "LCP2, EIF4EBP1, HCK, and PPP4C were demonstrated to be highly expressed, and SYNJ2 was demonstrated to be lowly expressed in atherosclerosis compared to the control group, which can be diagnostic biomarkers for patients with atherosclerosis." (PMID 35845072, 2022). "LCP2, EIF4EBP1, HCK, and PPP4C were demonstrated to be highly expressed and SYNJ2 was demonstrated to be lowly expressed in the atherosclerosis mice model." (PMID 35845072, 2022).
cystic kidneys (2 papers, 2022 to 2025). "In vivo, both agents similarly inhibited S6, eukaryotic translation initiation factor 4E-binding protein 1 (4E-BP1), and Akt phosphorylation, and reduced proliferation in cystic kidneys." (PMID 40801635, 2025).
esophageal cancer (2 papers, 2018 to 2022). A primary or metastatic malignant neoplasm involving the esophagus. "The relationship between EGR-1 expression and eukaryotic translation initiation factor 4E-binding protein 1 (4E-BP1) gene expression in esophageal cancer cells has been investigated." (PMID 36233659, 2022).